ERBB2 (erb-b2 receptor tyrosine kinase 2)
Diseases named in the same sentence as ERBB2 in open-access papers (continued):
Sharing a sentence is not in itself a finding about the gene and the disease.
breast cancer (continued). "Lack of expression of lipocalin 2, which is a secreted glycoprotein and involved in MMP-9 stability, delays ErbB2-induced mammary tumor metastasis with a mechanism that involves decreased MMP-9 activity." (PMID 24709902, 2014). "Based on this data we decided to study VRK1 protein expression in a panel of biopsies containing two groups of breast cancers, ER+/ERBB2- and ER-/ERBB2+." (PMID 24731990, 2014). "In a mouse model with spontaneously arising breast cancer due to erbB2-overexpression we show that exposure to porcine relaxin results in significantly enhanced tumour growth as compared to control animals." (PMID 23963762, 2014). "Consistent with this idea, the ERBB2/3 heterodimer has been demonstrated to be an “oncogenic unit” and a key factor in the proliferation and invasion of human breast cancer cells." (PMID 25248370, 2014). "It is of great importance to further investigate if lipogenesis regulated by acetylation of the Pparγ lysine motif (K154/155) contributes to the progression of ErbB2-positive breast cancer." (PMID 25229978, 2014). "The human epidermal growth factor receptor (HER)-2 (HER2/neu, c-erbB-2) is a transmembrane receptor that is overexpressed in 15–25% of breast cancers." (PMID 24634847, 2014). "In summary, these results suggest that the acetylation of the conserved lysine motif (K154/155) of Pparγ1 determines lipid synthesis in ErbB2-positive breast cancer cells." (PMID 25229978, 2014). "In a phage display study, EC1, an artificial peptide, was found to bind the extracellular domain of ErbB2 in living cells and fresh-frozen human breast cancer specimens." (PMID 25190023, 2014). "In breast cancer, amplification or overexpression of ERBB2 is a common event that appears in 15–30% of all specimens, and ERBB2 gene amplification and/or overexpression have been associated with a poor clinical outcome." (PMID 24937171, 2014). "For example, in ERBB2 (HER2) positive breast cancer, tumors that express high levels of β1 integrins develop more resistance to antibody inhibitors such as transtuzumab." (PMID 25198391, 2014). "The ErbB2 gene is amplified or overexpressed to various degrees in distinct types of human cancers, with an approximate frequency of 20%–30% in breast cancer." (PMID 24709906, 2014). "The Pparγ1 K154/155 determines the induction of lipogenesis in ErbB2 overexpressing breast cancer cells." (PMID 25229978, 2014). "A clinically well-established example is HER2 positive breast cancer characterized by overexpression of a member of the epidermal growth factor receptor family (ERBB2) playing a mechanistic role in progressive disease." (PMID 25364744, 2014). "In the last several years, our laboratory has focused on studying the unique biology of erbB3 receptor in the development of erbB2 aberrant breast cancer." (PMID 24886126, 2014). "Therapeutic ErbB2 inhibition is most beneficial at the early stages of breast cancer but much less efficient against invasive cancer that has already metastasized." (PMID 24709902, 2014). "The activation of ErbB2 is an early event in human breast cancer with ErbB2 overexpressed in up to 80% of primary ductal carcinoma in situ lesions." (PMID 24658544, 2014). "Targeting ErbB2/HER2 with the specific antibody trastuzumab has changed the standard of treatment and has improved prognosis for ErbB2/HER2-positive breast cancer patients." (PMID 24467886, 2014). "Tumors generated from PTEN-null/ErbB2-derived tumors, however, demonstrate characteristics similar to luminal-type human breast cancers." (PMID 25295225, 2014). "Overexpression of HER2, resulting from amplification of the ErbB2 gene, is observed in approximately 20% of breast cancers, and amplification of HER2 significantly correlates with increased disease aggressiveness and thereby with poor patient outcome." (PMID 25192037, 2014). "ERBB3 is frequently overexpressed in breast cancer and tends to function as an oncogenic unit by forming heterodimers with ERBB2." (PMID 25248370, 2014).
breast cancer (continued). "Gene amplification and overexpression of ErbB2, which occurs in 25% of all breast cancers, predicts for a poor clinical outcome as a consequence of increased tendency to metastasize to visceral organs earlier in the disease course." (PMID 24551203, 2014). "ERBB2 gene amplification and protein overexpression occurs in 20-30% of breast cancers and is reported to be a significant predictor of poor prognosis." (PMID 25343854, 2014). "Overexpression of p95 ErbB2 in mouse mammary gland under the mouse mammary tumor virus (MMTV) promoter facilitates mammary tumor metastasis to lungs in vivo over the full-length ErbB2." (PMID 24709902, 2014). "Concurrently, overactivation of the ErbB2 pathway correlates with poor clinical prognosis in breast cancer patients." (PMID 25280532, 2014). "Of particular interest is the antitumor activity of PUVA therapy in ErbB2+ breast cancer models of acquired therapeutic resistance to lapatinib and other ErbB2 targeted therapies." (PMID 24551203, 2014). "We found that PI-3 K/Akt-dependent upregulation of Survivin played a vital role in erbB3-mediated paclitaxel resistance in erbB2+ breast cancer cells, and specific knockdown of Survivin abrogated the resistance." (PMID 24886126, 2014). "Our data suggests that the antitumor effects of PUVA therapy in parental ErbB2+ breast cancer cells were mediated through direct effects on ErbB2." (PMID 24551203, 2014). "Trastuzumab, an inhibitory antibody to ErbB2 (human epidermal growth factor receptor 2 or HER2/neu) used in the treatment of breast cancer, can induce cardiac dysfunction and HF, suggesting an important role for ErbB2 in the heart." (PMID 25206341, 2014). "Identified members included those previously shown to be aberrantly silenced through DNA hypermethyaltion in UCC, e.g. IGFBP3, and those found to charactize breast cancer sub-types (e.g. ERBB2)." (PMID 25071007, 2014). "ErbB2/ErbB3 receptor activation, which occurs frequently in breast cancer, induces PI3K and Akt1 kinase activity." (PMID 24658544, 2014). "Taken together, in a mouse model of spontaneous erbB2-positive breast cancer, where interactions between tumour cells and the stromal compartment are not hampered by species barriers and immunodeficiency, relaxins clearly promote tumour progression." (PMID 23963762, 2014). "ErbB2 is also found in tumour cells, and trastuzumab, an ErbB2 monoclonal antibody, is used for the adjuvant treatment of ErbB2-positive breast cancer." (PMID 25215939, 2014). "It is especially prevalent in breast cancer where the therapeutic targeting of ErbB2 is well developed consisting of multiple treatment options." (PMID 24709902, 2014). "Our data strongly support the development of clinical studies to evaluate the efficacy of MM-121 in combination with trastuzumab or paclitaxel in therapeutically resistant erbB2+ breast cancer patients." (PMID 24886126, 2014). "We find that gene expression patterns within early neoplasias are distinct from both normal and breast cancer patterns and identify a pattern of pro-oncogenic changes, including elevated transcription of ERBB2, FOXA1, and GATA3 at this early stage." (PMID 24887547, 2014). "Human epidermal growth factor receptor 2 (ERBB2) is an important biomarker not only for breast cancer, but for other types of cancer prognosis and patient treatment decisions as well." (PMID 24926380, 2014). "Recently, it has been shown that lapatinib-induced apoptosis requires Bim and Puma in ERBB2-amplified breast cancer cells." (PMID 24970817, 2014). "An alternative form, known as the p95 ErbB2, is often expressed in highly invasive and metastatic breast cancers." (PMID 24709902, 2014). "Breast cancer cell lines known to express the target antigens ErbB2, EphA2, EphB3, and CD44 with high and low levels were stained with the identified phage mAbs and evaluated by fluorescence microscopy." (PMID 25353955, 2014).
breast cancer (continued). "The ErbB2+ breast cancer cell lines used in these studies express EGFR, which has also been shown to be a target of PUVA therapy." (PMID 24551203, 2014). "The mean vessel area in ERBB2-induced breast cancer tumors was in Hsf1-/- mice almost twice as small as in wild type animals." (PMID 24467529, 2014). "The classical example of this is amplification of Her2neu (ERBB2) in breast cancer, but that also was present in three of the CRC samples studied." (PMID 25394515, 2014). "The survival of breast cancer cells, especially those with ErbB2/Her2 overexpression, is highly dependent upon the lipid metabolism induced by Pparγ, which protects cells from palmitate toxicity." (PMID 25229978, 2014). "Here we show that porcine relaxin significantly enhances growth of breast cancers which had developed spontaneously in an erbB2-overexpressing mouse model." (PMID 23963762, 2014). "One of the most appealing aspects of amplifications is their possible association to drug therapy, with trastuzumab sensitivity in ERBB2(Her2neu) amplified breast cancer as a classic example." (PMID 25394515, 2014). "ERBB2 (HER2) is an important drug target in breast cancer and an increasingly important target in gastric cancer." (PMID 25326863, 2014). "A retrospective clinical study examining a large cohort of tamoxifen treated, ER + breast cancer patients found that the patients with co-expression of erbB2 and erbB3 were significantly more likely to relapse on tamoxifen." (PMID 24886126, 2014). "On the contrary, downregulation of miR-125b in other tumor types induces oncogenic pathways, e.g., ERBB2/3 signaling in mammary carcinoma." (PMID 24774301, 2014). "The four responding models belonged to two different breast carcinoma subtypes: three were basal like carcinomas (HBCx-7, HBCx-10, and HBCx-19) and one was an ERBB2-overexpressing breast carcinoma (HBCx-5)." (PMID 25375638, 2014). "The verified target genes v-erb-b 2 and 3 avian erythroblastic leukemia viral oncogene homolog (ERBB2/3), also named human epidermal growth factor receptor (Her) 2 and 3 are heavily upregulated in many invasive mammary carcinomas." (PMID 24774301, 2014). "These PDXs are allocated in 3 tumor subtypes: basal-like (17/25), ERBB2 positive (3/25) and luminal (5/25) breast carcinomas." (PMID 25375638, 2014). "Various cancer-related cell-surface proteins are known to be transported into the nucleus in several cancers, including ErbB2 (breast cancer), CD40 (lymphoma), and CD44 (breast cancer)." (PMID 23638030, 2013). "To assess the impact of PGC-1α on the expression of glutamine metabolism genes, we used clones of ERBB2/Neu-induced breast cancer cells with modestly increased expression of PGC-1α (α-1.1 and α-1.2) and control cells (Ctl-1)." (PMID 24304688, 2013). "Single nucleotide missense substitutions of this region of ERBB2 have also been reported in breast cancer, gastric cancer, and colorectal cancer." (PMID 23630663, 2013). "In accord with our finding, it has been reported that β-catenin was excluded from forming a heterodimer with TCF/LEF in some human ErbB2+ breast cancer cell lines." (PMID 24265712, 2013). "We therefore propose functional studies on these miRNAs to reveal more biological insights into their role regarding ERBB2 overexpression in breast cancer." (PMID 23601657, 2013). "To date, no clinical study has been initiated to test MM-121’s activity in breast cancer patients with erbB2+ tumors, particularly those become resistant to trastuzumab." (PMID 24215614, 2013).
breast cancer (continued). "Our previous studies indicated that elevated expression of erbB3 led to paclitaxel resistance in erbB2-overexpressing breast cancer cells via PI-3 K/Akt signaling-dependent upregulation of Survivin." (PMID 24168763, 2013). "Our results revealed that the serum CK levels in breast cancer patients, especially ERBB2+ breast cancer, were significantly lower compared with patients with benign breast disease." (PMID 23614022, 2013). "Recent clinical data showed a significant overall survival benefit of patients with heavily pretreated metastatic ERBB2-positive breast cancer upon dual ERBB2 blockade through trastuzumab and lapatinib." (PMID 23630663, 2013). "ERBB2/Neu-induced breast cancer cells with increased expression of PGC-1α (α-1.1 and α-1.2) displayed an elevated expression of lipogenic genes compared with control cells (Ctl-1)." (PMID 24304688, 2013). "ERBB2 gene amplification or overexpression of the HER-2 protein has beenidentified in 25% to 34% of human breast cancers." (PMID 24004819, 2013). "EC1, one of these artificial peptides, bound the extracellular domain of ErbB2 in living cells and fresh frozen human breast cancer specimens." (PMID 24069396, 2013). "We demonstrate that MBP-1 negatively controls ERBB2 expression in SKBr3 breast cancer cells and suggest a role for HDAC1 in this regulatory mechanism." (PMID 23421821, 2013). "We have reported that the underlying mechanism that elevated expression of erbB3 results in paclitaxel resistance in erbB2-overexpressing breast cancer cells is attributed to PI-3 K/Akt-dependent upregulation of Survivin." (PMID 24168763, 2013). "Together our data suggest that LKB1 loss cooperates with ErbB2 to promote primary tumor development and that loss of LKB1 signaling promotes a pro-growth metabolism of ErbB2-expressing breast cancer cells." (PMID 24280377, 2013). "The receptor tyrosine kinase ErbB2 is a breast cancer biomarker whose posttranslational modifications (PTMs) are a key indicator of its activation." (PMID 23710360, 2013). "PPARGC1A expression was highest in basal and ERBB2-enriched breast cancer subtypes, which have poorer prognosis than luminal A and B subtypes." (PMID 24304688, 2013). "In a small group of ErbB2-positive breast cancer patients treated with lapatinib, those whose tumors had elevated levels of FGFR2 had a shorter time to progression than the low FGFR2 group." (PMID 23343422, 2013). "Overall, these data provide clinical relevance to the notion that PGC-1α is a central regulator of glutamine metabolism in ERBB2+ breast cancer cells." (PMID 24304688, 2013). "Elevated expression of erbB3 receptor has been reported to induce resistance to therapeutic agents, including trastuzumab in erbB2-overexpressing breast cancer." (PMID 24215614, 2013). "We believe that MM-121 will exhibit therapeutic potential in all erbB2-positive breast cancer patients (not only those with strong erbB3-expressing tumors) as long as the tumors show active erbB3 signaling." (PMID 24168763, 2013). "Noteworthy, NCOA3 overexpression in breast cancer correlates with larger tumor size, higher tumor grade, as well as with the expression of ERBB2." (PMID 24304549, 2013). "Nonetheless, MM-121’s therapeutic potential against erbB2-overexpressing breast cancers that are resistant to chemotherapy and/or the erbB2-targeted therapy has not been explored." (PMID 24168763, 2013). "Estrogen receptor (ER), progesterone receptor (PR) and ErbB-2/human epidermal growth factor receptor 2 (HER-2) status are molecular markers used to determine breast cancer subtypes as well as targets for treatment." (PMID 23340795, 2013). "Similar to human ERBB2 driven breast cancer, tumors in ERBB2 transgenic animals show simultaneous increase in endogenous ERBB3 but not ERBB4 expression." (PMID 23593223, 2013).
breast cancer (continued). "To characterize the effect of LKB1 loss on tumor cell phenotype further, we next investigated the status of cell polarity in ErbB2-positive breast cancer cells with reduced LKB1 expression." (PMID 24280377, 2013). "We believe that this work reports the most complete characterisation of the cat ERBB2 gene in normal samples and cat mammary tumour lesions to date." (PMID 24386251, 2013). "We show that the transcriptional coactivator PGC-1α, along with the transcription factor ERRα, is a positive regulator of the expression of glutamine metabolism genes in ERBB2+ breast cancer." (PMID 24304688, 2013). "Hormonal independence of breast cancer can occur with disease progression and induction of ERBB2 signaling." (PMID 23593223, 2013). "This study proposes that the anti-proliferative effects of tamoxifen require repression of ERBB2 and that breast cancer cells acquire resistance by deregulating the mechanisms that normally repress ERBB2 transcription." (PMID 23192763, 2013). "Together, the metabolite flux experiments performed with PGC-1α and ERRα illustrate that they both play a central role in controlling glutamine-mediated forward and reverse CAC fluxes in ERBB2+ breast cancer cells." (PMID 24304688, 2013). "The receptor tyrosine kinase ErbB2 (HER2) is an important biomarker that is overexpressed in ~25% of all breast cancers, is a key drug target, and is a member of a biologically important family of tyrosine kinases." (PMID 23710360, 2013). "In a previous work, Rajasekara and collaborators (2008) studied the effect of nsSVs on the 3D structure of the human erbB-2 protein and its potential use in breast cancer therapy." (PMID 24386251, 2013). "In several studies of cat mammary tumours, alterations of the ERBB2 proto-oncogene have been described, mostly at the protein level." (PMID 24386251, 2013). "MCF7 cells exhibit several features of luminal-like breast cancer including retention of ER protein, whilst BT-474 harbour an ERBB2 amplification." (PMID 23750209, 2013). "Elevated expression of erbB3 rendered erbB2-overexpressing breast cancer cells resistant to paclitaxel via PI-3 K/Akt-dependent upregulation of Survivin." (PMID 24168763, 2013). "Breast cancer is commonly classified by the estrogen/progesterone (ER/PR) receptor status and the HER2 (ERBB2) amplification status." (PMID 24098490, 2013). "In human breast cancers the expression of estrogen/progesterone receptors (ER/PR), the human epidermal growth factor receptor 2 (HER2/ERBB2) and basal or myoepithelial markers is routinely assessed." (PMID 24098698, 2013). "We have reported that elevated expression of erbB3 confers paclitaxel resistance in erbB2+ breast cancer cells via a PI-3K/Akt-dependent mechanism." (PMID 24215614, 2013). "Among four members of the ErbB family, EGFR and ErbB2 play major roles in different types of breast cancer." (PMID 23408941, 2013). "This is consistent with the finding that other ErbB2 overexpressing breast cancer cells, SKBR3, BT474 and MCF7/HER-18 have low Notch transcriptional activity as measured by NICD binding to CBF-1 responsive elements in a luciferase reporter." (PMID 23457626, 2013). "In this manuscript, we report that the PGC-1α/ERRα axis is a key regulator of glutamine metabolism in ERBB2+ breast cancer cells." (PMID 24304688, 2013). "Mammary tumors also arose more rapidly and with greater multiplicity in WAP-tva mice than in MMTV-tva mice, consistent with previous evidence of alveolar or alveolar progenitor cells as the preferred cell of origin for ErbB2-initiated mammary tumors." (PMID 24381245, 2013). "In breast cancer, miR-125a and miR-125b were reported down-regulated in biopsy specimens and as tumor suppressors by mediating the ERBB2 and ERBB3 pathway or by targeting the ETS1 gene." (PMID 23321005, 2013).